ALDOA (aldolase, fructose-bisphosphate A)
Diseases named in the same sentence as ALDOA in open-access papers (continued):
Sharing a sentence is not in itself a finding about the gene and the disease.
tumor (continued). "Moreover, tumours arising after ALDOA depletion showed a marked reduction in proliferation, indicated by lower Ki67 positivity." (PMID 39833612, 2025). "It remains to be determined whether macrophage-specific ALDOA expression contributes to their pro-tumoral functions independently of tumor cell ALDOA." (PMID 41239433, 2025). "Immunohistochemistry further demonstrated stronger staining of ALDOA in tumor tissues." (PMID 41239433, 2025). "ALDOA-high tumors may represent a subset with intense glycolytic activity and potentially high tumor antigenicity, making them initially more visible to the immune system." (PMID 41239433, 2025). "Research has indicated that ALDOA may be upregulated in certain cancers, particularly within CAFs in the tumor’s surrounding tissues." (PMID 41584584, 2025). "Tumor samples with higher ALDOA expression exhibited more pronounced histopathological alterations." (PMID 41239433, 2025). "Mechanistically, this co-expression pattern suggests a potential therapeutic strategy: targeting ALDOA/ENO1-dependent glycolysis could disrupt tumor metabolic reprogramming." (PMID 41049005, 2025). "To verify whether TREM2+ macrophages regulate the expression of PKM, G6PD, and ALDOA in tumor cells, we detected their levels in Hepa 1–6 cells treated with CM from WT or Trem2−/− BMDMs." (PMID 39838454, 2025). "Targeting ALDOA-mediated glycolysis using metabolic inhibitors such as 2-DG or glycolysis inhibitors may disrupt tumor cell metabolism and impair tumor progression." (PMID 41239433, 2025). "Notably, ALDOA expression was considerably correlated with tumor size, invasion depth, LNM, and TNM stage (P = 0.001, 0.009, 0.001, and < 0.001, respectively)." (PMID 39755705, 2025). "Quercetagitrin did not further decrease the tumor volume in ESCC tumors harboring ALDOA Y174A, Y302A, or Y328A mutations." (PMID 40887473, 2025). "Furthermore, in vivo study showed that ALDOA overexpression in HepG2 cells remarkably increased tumor volumes and weights in nude mice." (PMID 40708574, 2025). "This suggests a potential role for ALDOA in genomic instability and tumor progression." (PMID 41239433, 2025). "Additionally, clinical evaluation demonstrated a positive correlation between high ALDOA expression and tumor size, invasion depth, LNM, and TNM stage." (PMID 39755705, 2025). "Notably, glycolysis enzymes (GPI, LDHA, LDHB, TPI1, and ALDOA) showed specific enrichment in exosomes from the primary tumor." (PMID 38419074, 2024). "Tumor tissues were then subjected to H&E and Ki67 immunohistochemistry experiments, which showed that ALDOA K230/322R treatment significantly reduced the number of proliferating cells in tumors compared to ALDOA WT‐treated LCSCs." (PMID 39099416, 2024). "Moreover, ALDOA levels in tumor tissues negatively correlate with the number of infiltrating immune cells, including macrophages, CD4+ T cells, and CD8+ T cells." (PMID 39201614, 2024). "Significantly, ALDOA is upregulated in many tumour types and this suggests that its upregulation may contribute to the metabolic reprogramming observed in tumours." (PMID 37704669, 2023). "Taken together, this suggests that targeting ALDOA may be an important anti-tumour strategy, particularly in tumours that are reliant upon glycolysis as an energy source, and may enable the concurrent targeting of cancer metabolism and DNA repair." (PMID 37704669, 2023). "Moreover, this study showcased the generation of iTSCs and the production of tumor-suppressive CM through two distinct approaches: ALDOA overexpression and the utilization of LIV." (PMID 37896207, 2023). "In addition to the utilization of P04, our approach encompassed the generation of iTSCs and the production of tumor-suppressive CM via two distinct methodologies: ALDOA overexpression and the application of low-intensity vibrations (LIV)." (PMID 37896207, 2023).
tumor (continued). "Building upon our preceding investigations, wherein several tumor-suppressive proteins, including Moesin and Enolase 1, were enriched in tumor-suppressive CM, prompting the conversion of both tumor and non-tumor cells into iTSCs, we turned our focus to the role of ALDOA." (PMID 37896207, 2023). "Interestingly, miR-329-3p knockdown or ALDOA overexpression partially attenuated the tumor-suppressive effects of PSMA3-AS1 knockdown." (PMID 37403106, 2023). "Importantly, administration of GalNAc‐conjugated siRNA targeting ALDOA effectively slows the tumor growth of orthotopic xenografts." (PMID 37431681, 2023). "Paradoxically, however, extracellular ALDOA acts as a tumor-suppressing protein in breast cancer." (PMID 37896207, 2023). "For instance, the muscle isoform ALDOA is one of the most abundant glycolytic enzymes in almost all cancer cells, and participates in many cellular processes providing cancer cell survival, proliferation, tumour invasion, and metastasis." (PMID 37449059, 2023). "The protein levels of LIPH and ALDOA in the tumor tissues were highly positively correlated." (PMID 37990271, 2023). "Interestingly, ALDOA overexpression partially rescued the tumor-suppressive role of PSMA3-AS1 knockdown in both GC cells and nude mice." (PMID 37403106, 2023). "The results of this study may provide comprehensive information of ALDOA in predicting the prognosis of tumor patients, and further investigation in the tumor immune microenvironment." (PMID 35804089, 2022). "ALDOA expression is directly related to tumor pathology, upregulated by hypoxic conditions, correlated with ROS genesis, glycolytic activity, growth potential, sphere formation, invasion, EMT phenotype, chemoresistance and radioresistance in colon cancer cells." (PMID 36077431, 2022). "Overexpression of ALDOA is believed to enhance glycolysis in tumor cells, promoting their growth." (PMID 35227895, 2022). "At the same time, we found that ALDOA may be co-expressed with TNFSF4 to regulate tumor immune infiltration." (PMID 35804089, 2022). "Thus, the upregulation of PINK1-AS and ALDOA in HCC is partly attributed to MKL-1 activation during tumour progression." (PMID 36494481, 2022). "Lactate depletion and tumor growth are inhibited by ALDOA knockdown." (PMID 36339430, 2022). "ALDOA acts as a potential tumor promoter via epithelial-mesenchymal transition (EMT) and the Wnt/β-catenin signaling pathway and may serve as a potential target for diagnosis and therapy." (PMID 35805203, 2022). "Targeting the ALDOA/FBP1 axis has also been considered as treatment to reduce tumor malignancy." (PMID 36077431, 2022). "Our results showed that ALDOA could be used as a biomarker for the tumor prognosis, and could be correlated with the infiltrating levels of macrophages, CD4+ T cells and CD8+ T cells." (PMID 35804089, 2022). "The interaction between ALDOA and ncRNA regulates tumor progression, a major research direction." (PMID 35804089, 2022). "Therefore, partially increasing the expression level of ALDOA has limited influence on the progression of the tumor." (PMID 33994862, 2021). "ALDOA plays a role in tumor mediation mainly through its enzyme activity level." (PMID 33994862, 2021). "In order to further reveal the mechanism behind the tumor-inducing function of ALDOA overexpression, we hope to inhibit the catalytic activity of ALDOA in the glycolysis pathway through its specific enzyme activity inhibitor and try to observe its effect on tumor cell proliferation and invasion." (PMID 33994862, 2021). "Multivariate regression analysis of clinical prognostic information demonstrated that ALDOA expression level may be correlated with multiplicity and tumor metastasis." (PMID 33994862, 2021). "We further demonstrated that the tumor suppressive effects of ARST could be mediated by a direct binding to ALDOA, which together with cofilin, maintains an orderly and strictly controlled balance of polymerization and depolymerization of actin filaments." (PMID 34099027, 2021).
tumor (continued). "Furthermore, they also illustrated that, during the progression of ICC, ALDOA mainly relies on its enzyme activity to exert its regulatory effect on tumor progression." (PMID 33994862, 2021). "This may be because that tumor cells themselves have a strong ability to proliferate and invade, and the pathway that ALDOA is involved in cannot completely determine the progress of the tumor." (PMID 33994862, 2021). "Further, by testing the glycolytic function with seahorse and detecting downstream metabolites of the glycolysis pathway by mass spectrometry, we found that the knockdown of ALDOA expression in tumor cells leads to a lower level of glycolytic products compared to that of control cells." (PMID 33994862, 2021). "Taken together, all these data suggested that the tumor suppressive role of ARST in gliomagenesis might be largely dependent on ALDOA." (PMID 34099027, 2021). "Similarly, knockdown of KCNQ1OT1 also promoted the expression of miR-34c-5p and inhibited the expression of ALDOA in tumor tissues from a subcutaneous xenograft mouse model." (PMID 32332718, 2020). "The increased expression of ALDOA significantly correlated with the depth of tumour invasion (T stage, P < .001), lymph node metastasis (N stage, P < .001), lymphovascular invasion (P = .001) and tumour diameter (P = .004)." (PMID 29992789, 2018). "As EMT is the initial step of cancer metastases, the relationship between the expression of ALDOA and EMT‐related marker was further validated, which suggested that ALDOA might promote tumour metastases by inducing the EMT process." (PMID 29992789, 2018). "To examine the relevance of this finding in the animal study, we detected the expression of ALDOA in PC-3-luc and PC-3-RR-luc s.c tumor xenografts and found the expression of ALDOA was increased in PC-3RR-luc s.c tumor xenografts compared with that in PC-3-luc xenografts." (PMID 28225015, 2017). "Consistently, strong staining of ALDOA was observed in the cytoplasm of the tumor cells." (PMID 24465716, 2014). "Similarly, high ALDOA expression was observed with increasing tumor grades and differentiation status." (PMID 24465716, 2014). "Moreover, given the strong correlation between ALDOA and macrophage-driven immune suppression, inhibiting ALDOA may enhance anti-tumor immune responses by reducing immunosuppressive macrophage polarization and increasing CD8 + T-cell infiltration." (PMID 41239433, 2025). "Inhibiting ALDOA could disrupt key tumor-macrophage crosstalk pathways in LUSC." (PMID 41239433, 2025). "Consequently, ALDOA upregulation in this context may be a biomarker of productive anti-tumor immunity but also a harbinger of an emerging metabolic checkpoint of resistance." (PMID 41239433, 2025). "Notably, the ALDOA gene exhibited downregulation in tumor tissues, suggesting that different stem cell marker genes may play distinct regulatory roles during tumorigenesis." (PMID 40766320, 2025). "However, when we measured ALDOA activity in crude enzyme extracts obtained from xenograft tumors, we observed lower activity in the sqr−/− derived tumor than that in the sqr+/+ derived tumor." (PMID 40305883, 2025). "Similar to Akt within the PI3K signaling cascade and β-catenin within the Wnt signaling pathway, we conjectured that the activation of oncogenic ALDOA within the intracellular domain could potentially yield iTSCs and engender the creation of tumor-suppressing CM." (PMID 37896207, 2023). "In addition, ALDOA is one of the most abundant glycolytic enzymes in tumor cells." (PMID 35804089, 2022). "Furthermore, whether there are other enzymes in the glycolysis pathway that could affect tumor progression like ALDOA." (PMID 33994862, 2021). "We further demonstrated that the tumor suppressive effects of ARST could be mediated by a direct binding to a glycolytic enzyme aldolase A (ALDOA), which together with cofilin, keeping the polymerization and depolymerization of actin filaments in an orderly dynamic equilibrium." (PMID 34099027, 2021).
tumor (continued). "Our results showed that ALDOA might be a tumor-promoting gene in LUAD." (PMID 33858449, 2021). "We evaluated whether ALDOA also modulates the tumor-initiating potential of lung CSCs." (PMID 32188842, 2020). "Importantly, to further confirm the existence of the DIO3OS/miR-122/ALDOA axis in PC tissues, we detected the levels of miR-122 and ALDOA in PC samples and non-tumor samples obtained from the TCGA database using the MethHC database and UALCAN web server, respectively." (PMID 31384177, 2019). "This study provides comprehensive evidence that ALDOA is a crucial oncogene in LUSC, driving tumor progression, immune evasion, and therapy resistance." (PMID 41239433, 2025). "Our immune deconvolution and ESTIMATE analyses consistently demonstrated that ALDOA-high tumors are characterized by significantly fewer CD8 + T cells and higher tumor purity." (PMID 41239433, 2025). "In the subcutaneous xenograft model, ALDOA knockout in HepG2 cells and HCCLM3 cells significantly inhibited tumor size and tumor weight compared to the sgCtrl groups, similar to the effects in vitro." (PMID 40708574, 2025). "Our results from IHC analysis showed ALDOA expression was positively correlated with CTGF and AREG expression in CRC tumor tissues." (PMID 39755705, 2025). "Meanwhile, ALDOA nuclear-positive cells appeared in liver tumor tissues, mainly after 6 months of DEN-treated, by the time of tumor development in the promotion and progression stages." (PMID 40708574, 2025). "According to both the LinkedOmics database and the GEPIA database, there was a positive correlation between ALDOA and ENO1 in both tumor and normal tissues." (PMID 41049005, 2025). "Herein, we observed that ALDOA content was reduced in HCT116 sqr−/− derived tumor xenografts, which should be one of the reasons why growth of tumor xenografts was significantly decreased." (PMID 40305883, 2025). "Among the essential genes identified in CAFs, ALDOA and CXCL12 stood out due to their potential implications in promoting tumor growth and metastasis." (PMID 41584584, 2025). "For example, core glycolysis genes such as ALDOA, GAPDH, ENO1, and PKM2 are high in both tumor and immune cells." (PMID 39774001, 2025). "Beyond its metabolic role, ALDOA has been increasingly recognised for its involvement in cancer progression by promoting EMT, metastasis and tumour progression." (PMID 41154605, 2025). "We then further evaluated the correlation between the IHC scores of ALDOA and p-AKT in 126 CRC tissues, and the results showed they were positively correlated in tumor tissues." (PMID 38499636, 2024). "The tumor volume and weight of the sh-ZNF692 and sh-ALDOA groups were significantly lower than those of the control group (P < 0.05)." (PMID 38453820, 2024). "Based on the expression of ALDOA and p-AKT in tumor tissues, we can effectively distinguish tumor tissues from normal tissues through cluster analysis." (PMID 38499636, 2024). "The results showed that ALDOA, ADH1B, and ALDH3B1 were significantly overexpressed in tumor samples compared to normal samples." (PMID 38256214, 2024). "LIPH directly bridges PDAC cells and tumor microenvironment to facilitate aberrant aerobic glycolysis via activating LPA/LPAR axis and maintaining ALDOA stability, which provides an actionable gemcitabine-based combination therapy with limited side effects." (PMID 37990271, 2023). "RNA sequencing and immunoprecipitation showed that LIPH participates in tumor glycolysis by stimulating LPA/LPAR axis and maintaining aldolase A (ALDOA) stability in the cytosol." (PMID 37990271, 2023). "In addition, LOXL2 catalyses the deacetylation of fructose-bisphosphate aldolase A (ALDOA) at K13, leading to the mobilisation of aldolase A from the cytoskeletal to the cytosolic fraction, which enhances glycolysis and subsequently promotes tumour progression." (PMID 37762708, 2023).
tumor (continued). "We also identified ALDOA as a biomarker of the MRS2 phenotype, and detected considerable infiltration of M2 macrophages and Tregs in the ALDOAhigh tumor tissues of the MRS2 patients." (PMID 36937389, 2023). "Depletion of ALDOA leads to depletion of lactate and attenuation of tumor growth, whilst knockdown of YTHDF2 rescues ALDOA expression in FTO-silenced HCC cells, implying its role in posttranscriptional regulation of ALDOA under hypoxia conditions." (PMID 36289851, 2022). "The expression of differential genes related to PPP, including TKT, TKTL1, PGM1, GPI, FBP2, ALDOA and ALDOC, were all upregulated in WDLPS tumor samples, which were validated by Real-time Quantitative PCR (RT-qPCR)." (PMID 36557266, 2022). "The expression levels of key glycolytic enzymes, namely GLUT1, ENO1, PGK1, ALDOA, HK1, and LDHA, in the tumor tissues of chemotherapy-resistant and chemotherapy-sensitive groups were examined using IHC analysis." (PMID 34510316, 2022). "Identical results demonstrated that an opposite trend between ALDOA and FBP1 was observed between normal and tumor groups." (PMID 35404841, 2022). "Seven genes, PFKFB4, ALDOA, EGLN3, EHHADH, GAPDH, HMGCS2, and ENO2, related to tumor FDG uptake were revealed to have a good prognostic value for survival in HCC." (PMID 35174098, 2022). "In a hypoxic environment, ALDOA can mediate EMT in tumour cells by regulating hypoxia inducible factor-1α (HIF-1α), which enhances tumour cell migration." (PMID 36494481, 2022). "In the normal and tumor groups, patients with low FBP1 expression had high ALDOA expression (p<0.0001)." (PMID 35404841, 2022). "The top genes in cold tumor are ARF1, PDIA3, ALDOA, FKBP2, NDUFS5, NDUFC1, COX7A2, C14orf2, LNX1, and BTBD6." (PMID 33816503, 2021). "To validate the expression level of ALDOA in ICC tissues, we collected clinical tumor tissue samples from patients, who were treated surgically and diagnosed post-operatively with ICC at Renji Hospital." (PMID 33994862, 2021). "Our study also confirmed that the high expression of ALDOA promoted the progress of ICC, and Itaconate can directly inhibit the glycolysis level of ICC tumor cells and thus affect tumor progression." (PMID 33994862, 2021). "Regarding the molecular mechanism, we found that ALDOA inhibited the DDR and improved activation of the cell cycle checkpoint PLK1 by suppressing ATM, which promotes tumour cell progression." (PMID 34565365, 2021). "In vitro and in vivo experiments using the ALDOA inhibitor TDZD-8, 1,2,4-thiadiazole demonstrated a decreased cell proliferation and a reduction in tumor growth due to a lower glycolytic activity." (PMID 33804240, 2021). "HIF-1α accumulation contributes to glycolysis by enhancing transcription of glycolysis-related genes, including GLUT1, HK2, ALDOA, PKM2, and LDHA, which was the most important method for tumor cells to get energy and growth." (PMID 33244454, 2020). "The inhibition of metabolic enzymes such as ALDOA, GAPDH or FASN can prevent or revert EMT in cell models, as can the neutralization of acidic tumor environments." (PMID 31277295, 2019). "The results indicated that the up‐regulated expression of ALDOA and down‐regulated FBP1 were most significant in liver metastases compared with its primary tumour." (PMID 29992789, 2018). "Collectively, this study provided firm evidence that ALDOA was crucial in GC by inducing the EMT pathway and affecting HIF‐1α activity in tumour progression and metastasis." (PMID 29992789, 2018). "Two genes (ALDOA in module 5 and LEPROTL1 in module 2) also belonged to modules that significantly and positively correlated with proximity to tumour." (PMID 29093438, 2017). "The total metabolic tumor volume (MTV) is a direct consequence of the alterations in the expression levels of glucose transporter 1 (GLUT-1), fructose bisphosphate aldolase A (ALDOA), and fructose bisphosphatase 1 (FBP1)." (PMID 28335509, 2017).